U8 (U8 small nucleolar RNA )
Synonyms: LOC124900257
Gene: Small nucleolar RNA gene on chromosome 8 (71,815,494 to 71,815,625, reverse strand). Ensembl gene ENSG00000200191.
Gene Ontology:
Biological process: RNA processing
Cellular component: nucleolus
Homologues: Orthologues: chimpanzee U8 (99% identical), macaque U8 (94% identical). Paralogues in human: U8 (81% identical), U8 (80% identical), U8 (79% identical), U8 (77% identical), U8 (76% identical), U8 (74% identical), U8 (73% identical), U8 (71% identical), U8 (70% identical), U8 (66% identical), U8 (63% identical), U8 (62% identical), and 2 more.